CCL2 (C-C motif chemokine ligand 2)
Diseases named in the same sentence as CCL2 in open-access papers (continued):
Sharing a sentence is not in itself a finding about the gene and the disease.
infection (continued). "To assess whether proinflammatory chemokines induced by decidual cell infection contribute to the reduced ability of trophoblasts to form tubular structures, we repeated the tubulogenesis assays by pre-incubating the CM with neutralizing antibodies against CXCL8 and CCL2." (PMID 40943115, 2025). "In addition, higher levels of CCL2/MCP-1, IL-6, and Macrophage inflammatory protein-1 (CCL4/MIP-1β) and decreased levels of Regulated upon Activation, Normal T-cell Expressed and Secreted (CCL5/RANTES) are observed in the chronic phase of infection and arthritic cases." (PMID 38543735, 2024). "Similarly, the chemokines CCL2 (attracting monocytes), CXCL2 (attracting neutrophils), CCL5 (attracting T cells), CXCL10 (attracting activated T cells, eosinophils), and CCL11 (eosinophils) were elevated during infection with a significant reduction in TLR7 KO mice." (PMID 39769461, 2024). "Furthermore, a significantly reduced intracellular Fn was observed in the si-CCL2/7 group compared with the negative control siRNA (NC-siRNA) group at 24 h post-infection, whereas the amount of intracellular Fn was partially restored in the Fn-Dps-treated si-CCL2/7 group." (PMID 36693067, 2023). "Mice lacking CCL-2 or its receptor CCR-2 are characterized by a reduced Tip-DC frequency in Lm-infected spleens resulting in uncontrolled bacterial growth, thus underlining the importance of monocyte-derived dendritic cells, originating from Ly6Chigh monocytes, for the outcome of infection." (PMID 36618344, 2022). "As a first step, an investigation was launched into whether M. leprae was able to induce the secretion of the chemokines MCP-1 (CCL2) and IL-8 (CXCL8) in alveolar type II pneumocytic epithelial A549 cells, known to play an important role in mediating immune cell migration to the infection site." (PMID 34456901, 2021). "Moreover, EBN restores the immune system in the context of infection by influencing viruses through regulation of pro-inflammatory cytokines, such as IL-6 and TNF-α, and cytokines with regulatory properties, such as IL-10 and CCL2, which are also involved in the progression of UC." (PMID 33967768, 2021). "Surprisingly, the chemokines responsible for susceptibility could not be identified either individually or in combination: mice deficient in MCP-1/CCL2, MCP-3/CCL7 KO mice, or MCP-5/CCL12, the major known murine ligands for CCR2, were not unusually susceptible following ID LVS infection." (PMID 33760886, 2021). "Our results demonstrated that vaccination with pcHrp1 or pcHrp1+pcIL-34 could significantly trigger the expression of IL-8, CCL2, CXCL9, CXCL10, and CCL20, indicating that the chemokines were involved in the recruitment of neutrophils, monocytes, Th1 cells, and Th17 cells to the infection sites." (PMID 32231137, 2020). "Finally, a marked increase in inflammatory chemokines MIP-1β/CCL4, MCP-1/CCL2, and IL-8/CXCL8, accompanied by an increase of inflammatory cytokines IL-15, IL-12, TNF-a, GM-CSF, and G-CSF, which was detected in the lung predominantly at day 7–9, the middle and late stage of infection." (PMID 33180882, 2020). "Moreover, infection with lethal strains of SARS-CoV demonstrated worse lung pathology and higher levels of induction of inflammatory chemokines, such as Cxcl10 and Ccl2, than infection with non-lethal SARS-CoV strains that replicated to similar or even higher levels in the lung." (PMID 33613280, 2020). "We found increased levels of IL-1β, CCL2, and CCL3 concomitant with elevated neutrophil infiltrates in the CSF of animals with S. epidermidis-infected catheters, which may serve as potential markers for distinguishing infection from sterile postoperative inflammation in humans." (PMID 31262978, 2019).
infection (continued). "Likewise, brain tissues of animals with S. epidermidis-infected catheters had higher levels of IL-10 (P < 0.001), IL-1β (P < 0.001), CCL2 (P < 0.001), and CCL3 (P < 0.001) at day 1 postinfection, demonstrating that the CSF inflammatory milieu mirrors that of the brain tissue during early infection." (PMID 31262978, 2019). "Additionally, the same authors also found viral RNA in the CSF of a different cohort of hRSV-infected patients, with increased levels of IL-6, IL-8, CCL2, and CCL4, suggesting that these inflammatory mediators may play a critical role during the hRSV-infection in the CNS pathogenesis." (PMID 30936869, 2019). "Consequently, CCL2, CCL3, and CCL9 produced by HSPCs may activate and attract neutrophils, monocytes and dendritic cells, therefore contributing to another level of protection against infection." (PMID 30234030, 2018). "The maintenance of a minimal level of CCL2 following AFSC treatment, may be critical for the protection of the homeostatic arm of the CCL2/CCR2 signaling pathway which not only participates in immune cell recruitment to areas of infection but also osteoclast differentiation and metabolic regulation." (PMID 23967234, 2013). "Since we observed a NOD2-dependent increase in CCL2, type I IFNs and circulating monocytes following MDP treatment of IAV-infected mice, we investigated whether such treatment affected populations of monocytes, neutrophils and macrophages in the lungs during the course of infection." (PMID 22590599, 2012). "Regardless of sex, infection induced upregulation of IL‐10, IL‐8, and TNF, alongside downregulation of CCL2 and IL‐18 in the supernatant of infected cells." (PMID 41546136, 2026). "In addition, these results suggest that, particularly in the case of CM Bs, whose inhibitory effect on trophoblast chemotaxis was not reversed by CXCL8 or CCL2 neutralization, other infection-induced mediators not evaluated in this study may be involved in the modulation of this chemotactic process." (PMID 40943115, 2025). "Although the expression of CCL2, CCL5 and TNF was not as robust as IFN-β, there was a pattern of activation after infection, which was mildly inhibited by G140 for CCL2 and CCL5." (PMID 41139159, 2025). "Surprisingly, compared to uninfected HIBCPP cells, infection with C. albicans did not alter the secretion of CXCL8, CCL2, and CCL5 after 24 h, respectively, which was the fact for both the basolateral (blood) and apical (CSF) side." (PMID 40181464, 2025). "Consistent with the lack of effect on BR15 infection, AbII treatment did not significantly alter the levels of IL-1β, IL-6, IL-10, CCL2 (MCP-1), CCL5 (RANTES), or CXCL8 (IL-8) in BR15-infected cells." (PMID 40732762, 2025). "When measuring mRNA expression levels from BAL cells, chemokines CCL2, CCL5, CCL8, and CXCL10 and receptors CCR5 and CXCR5 were significantly upregulated only in JBNU-22-N01 infection at 7 dpi compared with the negative control." (PMID 40459260, 2025). "Furthermore, SARS-CoV-2 D614G[Omicron spike] infection resulted in a significantly increased expression of ISGs Mx1, Oas1, and Viperin as well as Cxcl10, while pro-inflammatory mediators Cxcl1, Ccl2, and Il6 were not significantly altered in any group compared to the uninfected mice." (PMID 38742107, 2024). "CCL-2 exhibited heightened levels on day 1 post-infection, while IL-1β, IL-13 and CCL11 showed increased levels on both day 1 and 4 post-infection, as compared to the non-infected group." (PMID 39038037, 2024). "We thus identified several alternative inflammatory genes whose expression was either completely (Cxcl1) or partially (Ccl2 and Il6) independent of IFNAR1 signaling following infection." (PMID 38011306, 2023). "Our study also shows that trypomastigote lysate, OGE fractions and rTcMIP were all able to trigger IFN-γ, CCL2 and CCL3 responses by human umbilical cord cells, indicating that the immune-stimulating effect did not depend on cell infection." (PMID 37033946, 2023).
infection (continued). "Inhibition of miR-223-3p did not impact levels of CCL2, IFN-stimulated gene 15 (ISG15), or IL-6 in either SARS-CoV-WT or ΔE infection at any time point." (PMID 35229638, 2022). "Other cytokines, namely TNF-α, IFN-γ, CCL2, and TGF-β, showed no significant changes following the polymicrobial infection or nisin treatment, although the anti-inflammatory cytokine TGF-β showed a trend toward higher levels with nisin treatment." (PMID 35672331, 2022). "The analyses revealed that, compared to the H7N9 infection, the H9N2 infection induced an earlier induction of both CCR2 and CXCR4 transcripts, similar to that of CCL2 in the lung (data not shown)." (PMID 36034707, 2022). "Here, we confirmed that spleens of both wild type and CCR2 KO mice contained MCP-1/CCL2 and MCP-5/CCL12 within two days of LVS infection; reagents to quantitate MCP3 were not available." (PMID 33760886, 2021). "At early time points, Fpr2-/- mice showed a significant decrease in CXCL1, CXCL2, IL-1β, CCL2, GM-CSF, IL-6, and CCL3 levels at 1 hour and 3 hours after infection, and an increase in IL-22 and IL-23, but there is no change in TNF-α, as compared with WT mice." (PMID 34899755, 2021). "In contrast to CCL2, both the lack of CXCL1 during TMEV infection and the excessive presence of this chemokine promote the pathogenesis of demyelinating disease." (PMID 34067536, 2021). "Consistent with previous findings, LCMV-infected WT mice showed a significant increase of CCL2 on day 3 postinfection and IL-5 on day 7 postinfection, only, while TNF, IL-1β, IL-6, IFN-γ, CCL1 and CCL22 levels did not change following infection." (PMID 32310998, 2020). "histolytica infection, TNF and CXCL1, but not CCL2, were produced by Ly6Chi monocytes with a clear bias towards males." (PMID 32651360, 2020). "TNF-α, IL-6, CXCL1, CCL2, and CCL7 levels significantly increased in the sera of klotho WT and KO mice at 1 day post-infection, while the level of IL-12 was not." (PMID 33329595, 2020). "Although there was a modest increase of XCL1, CCL2, CXCL2 and CXCL10 mRNAs in these mice following infection, this was not statistically significant." (PMID 32310998, 2020). "We also found that protein levels of IL-6, IL-12p40, IL-12p70, CCL2, CCL3 and CCL4 were not suppressed in response to rosiglitazone treatment during super-infection." (PMID 31159430, 2019). "The induction of cytokines (IL6 and TNFα), chemokines (CCL2 and CXCL10), and IFN-I genes in primary C57BL/6 astrocytes following a TMEV-BeAn infection can be mediated by TLR3 but not TLR7 or other MyD88-mediated pathways." (PMID 30669615, 2019). "In the zebrafish, 1–3 Mm are sufficient to establish infection in the majority of zebrafish larvae provided that bacterial PGL and host Sting and Ccl2-Ccr2 are present; without these factors, infectivity is reduced." (PMID 28844797, 2017). "There were minimal levels of serum IL-6, CCL2, CXCL1, and TNF-α in mice without CVB3 infection, while those infected with CVB3 had significantly increased inflammatory cytokines and chemokines on day 5 post infection, which might be associated with exacerbation of pancreatic inflammation." (PMID 27195463, 2016). "CSF2 and CCL2 protein levels were higher in CF cells than in CTRL cells and increased further with time after infection, although the differences were not statistically significant." (PMID 26485688, 2015). "At 18 h and 96 h post infection (p.i.), no IFN-α, IL-6, CXCL10 or CCL2 was detected in the bronchoalveolar lavage fluid (BAL) of infected MTM−/− mice, in contrast to BAL from wt animals." (PMID 26688048, 2015). "To this end, we found that administration of poly I:C, a TLR3 ligand, to RAG−/− mice throughout the first six weeks of infection, resulted in up-regulation of splenic mRNA for IL-1β, TNF, and CCL2, rather than their down-regulation." (PMID 24130499, 2013).
infection (continued). "On day 7 p.i., in addition to chemokines upregulated on day 3 p.i., lethal infection further induced higher expression of CCL2, CCL6, CCL11, CCL19, CCR7, CXCR1, and CXCL11 compared to nonlethal infection." (PMID 23526993, 2013). "Infection with M. marinum strains lacking PGL resulted in fewer macrophages being recruited to the site of infection, which was rescued by adding in the CCR2 ligand, CCL2." (PMID 40304497, 2025). "Notably, deficiency in endothelial Sparcl1 reduced the levels of the classical monocyte chemoattract CCL2 (also known as MCP-1) in BALF and serum (not significant) during infection (day 12)." (PMID 38762489, 2024). "The MOIs of 0.1 and 1 used to treat endothelial cells produced significant amounts of pro-inflammatory cytokines IL-6 and CCL2, so the MOI of 1 was chosen for the subsequent experiments as a way to mirror direct infection of brain endothelial cells, but not microglia and astrocytes." (PMID 39474424, 2024). "In addition, the expression of CCL2, CXCL10 and IL-6 represented a non-significant difference with the infection of SC16, HN10 and CVS-11." (PMID 39273091, 2024). "Compared to infection without rAb-ADA, the co-administration of DENV-2 and rAb-ADA resulted in a substantial increase of inflammatory mediator genes IL-1β, IL-6, TNF-α, and CCL2 in Raw264.7 and THP-1 cells." (PMID 37794048, 2023). "ONNV failed to increase CCL2 and CXCL8 protein levels at 24 h and also at 30 h post infection." (PMID 36611893, 2022). "TNF, CCL2, and CXCL1 were mainly produced by ex vivo-restimulated liver-derived Ly6Chi monocytes from E. histolytica-infected male and female mice on Day 3 post-infection (p.i.), rather than by Ly6Clo, Ly6Cneg, Ly6G+, and CD11bneg cells." (PMID 32651360, 2020). "However, the systemic concentrations of some pro-inflammatory cytokines (IL-6 and CCL2), but not all (TNF-α, IL-1α, and IL-1β), were slightly over-induced in Ripk1LPC-KO mice at late stage of infection (72 hpi)." (PMID 30622241, 2019). "We observed secretion of several chemokines in response to T. cruzi infection (CCL2, CXCL5 and CXCL10), which indicate that despite the lack of inflammatory cytokines, the macrophages are not completely immunologically unresponsive to infection." (PMID 31841511, 2019). "Albeit not statistically significant, the levels of G-CSF, IL-1α, MCP-1/CCL2, MIP-2/CXCL2 at day 1, G-CSF, KC, MCP-1, and MIP-2 at day 2, and IL-1α, IL-1β, IL-6, IL-10, MCP-1, MIP-2, and TNF at day 3 post-infection were 1.5–4.4-fold higher in SIRT3/5−/− than in SIRT3/5+/+ mice." (PMID 31632409, 2019). "Our results showed that topical LTB4 decreased lesion size and bacterial clearance in macrophage-depleted mice, restored production of the chemokines, CCL2 and CXCL4, but not CXCL2, VEGF, IL-33, and IL-1β and neutrophil migration to the site of infection in DT-treated MMDTR mice." (PMID 30102746, 2018). "CC chemokines including CCL2 and CCL20 were significantly induced upon HRV72 infection suggesting that non-neutrophilic immune response could be potentially provoked by this virus." (PMID 28558071, 2017). "The production of CCL-2 did not occur until 12 h post-infection, but then increased from 24 to 48 h post-infection, while the secretion of IP-10 and TNF-α increased gradually peaking at 36 h post-infection." (PMID 28127293, 2016). "To verify that anti-CCL2 Ab did not affect reverse transcriptase (RT) activity and early post-entry events, we evaluated HIV-1 DNA synthesis by semi-quantitative PCR assay at 24 h post-infection." (PMID 25608886, 2015). "However, infection of mice with mouse-adapted RAVV induces increased IFN-γ, IL-5, IL-12, CCL2, and CXCL9 relative to infection with non-lethal RAVV." (PMID 26426036, 2015). "Infection of epithelial cells resulted in significantly increased secretion of the neutrophil chemotactic CXCL8 and IL-6, but no secretion of monocyte chemotactic CCL2 or TNF-α was observed." (PMID 22058091, 2012).
infection (continued). "Interestingly, whereas TLR4 inhibition (TAK-242, 10 μM) did not alter enhanced OAS1 and IRF7 expression in response to hypoxic priming and SARS-CoV-2 infection, it completely abolished the expression of chemokine ISGs CCL2 and CXCL10, despite the fact that the infection rate was not affected." (PMID 37377965, 2023). "In the mutant strain infection, we noted that Th17-related cytokines (IL-17A, IL-22) and neutrophil-related chemokines (CCL2, CCL3, CXCL1, CXCL2) are significantly reduced at the early stage of infection, which might be related to the absence of melanin and defects in growth and germination." (PMID 35696422, 2022). "Similarly, infection of adult BALB/c mice with a mouse-adapted H3N1 influenza A virus results in greater lung hyperresponsiveness to methacholine challenge and production of CCL2, but not virus titers, in females compared with males." (PMID 21829352, 2011). "Following CB4 challenge, TLR3KO mice produced similar levels of CCL2 and CXCL9 while levels of CCL3 and CCL4 were slightly reduced but were not significantly different from either WT NOD controls or MyD88KO mice suggesting that these chemokines are not critical for survival following infection." (PMID 19122812, 2009).